CARD9 (caspase recruitment domain family member 9)
Diseases named in the same sentence as CARD9 in open-access papers (continued):
Sharing a sentence is not in itself a finding about the gene and the disease.
inflammatory bowel disease (25 papers, 2009 to 2025). A spectrum of small and large bowel inflammatory diseases of unknown etiology. "Studies have shown that Card9-deficient mice, which lack protective alleles against inflammatory bowel disease (IBD), display increased susceptibility to colitis and impaired TRP metabolism by the intestinal microbiota." (PMID 39867340, 2024). "Caspase recruitment domain family member 9 (CARD9) has been implicated as one of many inflammatory bowel disease susceptibility genes." (PMID 35008717, 2021). "Genetic susceptibility to inflammatory bowel disease due to deletion of the caspase recruitment domain family member 9 (Card9) gene is associated with an altered microbiota that has an impaired capacity to metabolize Trp to AhR ligands." (PMID 31125257, 2019). "One intriguing CARD9 splice variant, identified as protective in inflammatory bowel disease, eliminates a TRIM62 binding site, preventing CARD9 signaling and bolstering the idea that TRIM62 ubiquitination of CARD9 is critical for its activation." (PMID 31296852, 2019). "Upon activation, dectin-1 signaling converges, similar to NOD2, on the adaptor molecule CARD9 which is associated with inflammatory bowel disease (IBD)." (PMID 19915667, 2009). "Additionally, the immune-regulatory genes NOD2 and CARD9 are associated with shifts in Enterobacteriaceae populations, particularly in individuals predisposed to inflammatory bowel disease (IBD)." (PMID 40430189, 2025). "The trans-eQTLs contributing to this association with GATE scores for ISGs include IFIH1, IKZF1, and CARD9, previously reported as GWAS hits for inflammatory bowel disease." (PMID 40996888, 2025). "The CARD9 gene is a GWAS candidate gene for ankylosing spondylitis (AS) and inflammatory bowel disease (IBD)." (PMID 36002455, 2022). "CARD9 is involved in gut homeostasis and plays a crucial role in the development of diseases such as inflammatory bowel disease (IBD) and colorectal cancer." (PMID 33732234, 2021). "Along with an in‐depth understanding of pathological CARD9 signalling, CARD9 was confirmed to play an essential role in the pathogenesis of inflammatory bowel diseases." (PMID 31696662, 2020). "Moreover, CARD9-dependent functions have recently been indicated to modulate the development of autoimmunity, inflammatory bowel diseases, and cancer." (PMID 30127791, 2018). "Genome-wide association studies (GWASs) in IgAN support that galactose-deficient IgA1 (Gd-IgA1) is heritable, and they also suggest that some GWAS loci, such as CARD9, TNFSF13, and PSMB8, are shared among IgAN, inflammatory bowel disease (IBD), and bacterial infections." (PMID 33436510, 2021).
candidiasis (22 papers, 2011 to 2025). Infection with the organism Candida. "CARD9-deficient patients can eliminate Candida through neutrophil IgG opsonization, thereby preventing invasive Candida infections." (PMID 41041311, 2025). "A model of candidiasis that accurately recapitulates human CARD9 deficiency is invaluable to decipher its immunopathogenesis." (PMID 40424070, 2025). "Overall, these results not only confirm that loss of CARD9 function confers susceptibility to invasive candidiasis but also that it does so by decreasing the threshold of C. albicans inoculum required to cause disease." (PMID 40424070, 2025). "The invasive candidiasis of CARD9 deficiency is most commonly caused by C. albicans, chronic in nature, and late in disease onset and has an unexplained predilection for the CNS." (PMID 40424070, 2025). "In CARD9 deficiency (see the “Candidiasis” section presented above), both CPA and extra-pulmonary disease without concomitant lung involvement (e.g., intra-abdominal, CNS, and cutaneous) have been observed." (PMID 36986378, 2023). "Although mainly associated with candidiasis, CARD9 deficiency is increasingly being linked to susceptibility to a wider range of fungal infections, including Aspergillus." (PMID 36012793, 2022). "During subcutaneous candidiasis, Card9–/– mice were susceptible, showing increased footpad swelling and fungal burden compared with WT mice." (PMID 36377664, 2022). "The present data seemingly contrast with observations in neuroinvasive fungal diseases (candidiasis) in CARD9−/− mice and humans with inherited CARD9 deficiency, showing that the adaptor protein critically controls brain infection." (PMID 34209576, 2021). "In a subsequent study, additional understanding was obtained on the invasive nature of candidiasis resulting from mutations in CARD9 gene." (PMID 29371502, 2018). "Immunity to C. albicans, the most frequent species to be isolated in candidiasis, involves a well-characterized Dectin-1/caspase-associated recruitment domain adaptor 9 (CARD9)/IL-17 signaling axis." (PMID 26336150, 2015). "In patients with intact CARD9 signaling, systemic candidiasis is most often associated with the kidney, liver and spleen." (PMID 26679537, 2015). "For this, we used Card9-/- mice that are significantly more susceptible to systemic candidiasis, as has been previously shown." (PMID 26679537, 2015). "Recognition of C. albicans by dectin-1 triggers CARD9 signalling, and mutations in CARD9 lead to chronic mucocutaneous candidiasis and invasive Candida infections in humans." (PMID 24106515, 2013). "While CARD9 is clearly implicated in the protection against Candida infections, it has yet to be shown to what extent immunity to other pathogenic fungi is CARD9-dependent." (PMID 21267996, 2011). "Thus, the Y91HKI mouse is a newly developed tool to potentially understand the immunological mechanisms by which CARD9 regulates susceptibility to candidiasis." (PMID 40424070, 2025). "CARD9 deficiency causes chronic central nervous system (CNS) candidiasis." (PMID 40424070, 2025). "Thus, we next investigated the neutrophil response in the brain during the early stages of chronic invasive candidiasis in our low-dose, CARD9-deficient mouse models." (PMID 40424070, 2025). "The relevance of CARD9 is highlighted by the fact that CARD9-deficient mice are more susceptible to invasive candidiasis than wild-type mice and that humans with loss-of-function mutations in CARD9 likewise exhibit greater susceptibility to invasive candidiasis." (PMID 37900321, 2023). "CARD9 deficiency has been demonstrated to cause reduced cytokine production by human patient peripheral blood mononuclear cells and impaired neutrophil recruitment in in vivo mouse models, leading to increased susceptibility to systemic candidiasis." (PMID 36012793, 2022).
candidiasis (continued). "Interestingly, a large proportion of CARD9-deficient patients develop systemic candidiasis that specifically targets the central nervous system (CNS) without persistent fungemia." (PMID 26679537, 2015). "Therefore, other factors in addition to CARD9-mediated C. albicans yeast killing by phagocytes are likely to also contribute to the susceptibility of CARD9-deficient patients to Candida infection of the CNS." (PMID 26679537, 2015). "Therefore, this striking CNS-targeted manifestation of systemic candidiasis in CARD9-deficient patients suggests that CARD9 is uniquely required for protecting the CNS from fungal invasion." (PMID 26679537, 2015). "Importantly, we phenocopied for the first time the human CNS susceptibility to Candida infection of CARD9-deficient patients in Card9-/- mice which developed uncontrolled brain infection, evidenced by significantly higher brain fungal burdens as early as 24 hours post-infection." (PMID 26679537, 2015). "We established a knock-in mouse homozygous for the recurring p.Y91H mutation (Y91HKI) and, in parallel to Card9-/– mice, titrated the intravenous fungal inoculum to the CARD9 genotype to develop a model of chronic invasive candidiasis." (PMID 40424070, 2025). "Evidence suggests that CARD9 knockout leads to impaired antifungal immunity and aggravated Candida infection." (PMID 38566195, 2024). "Most studies have shown that CARD9 in myeloid cells participates in host resistance against invasive Candida infection." (PMID 38566195, 2024). "Our invasive candidiasis experiments now revealed that Syk and CARD9 in hematopoietic cells contribute to systemic resistance to C. parapsilosis." (PMID 34465030, 2021). "The autosomal recessive inheritance of loss-of-function mutations in caspase recruitment domain-containing protein 9 (CARD9) gene, were first described in a large consanguineous Iranian family with recurrent mucocutaneous and invasive Candida infections." (PMID 29371502, 2018). "To directly examine the role of CARD9 in CNS antifungal defense, we moved to a mouse model of systemic candidiasis using Card9-/- mice." (PMID 26679537, 2015). "Congenital immunodeficiencies with candidiasis, T lymphocyte dysfunction, and IL-17 deficiency have been described in the context of pathogenic variants in genes such as STAT3, CARD9, DOCK8, ACT1, IL-17RC, IL-17RA, and IL-17F—where fluconazole is the first-line treatment." (PMID 40686918, 2025). "Here, we show that a patient with CARD9 deficiency had impaired neutrophil accumulation and induction of neutrophil-recruiting CXC chemokines in the cerebrospinal fluid despite uncontrolled CNS Candida infection." (PMID 26679537, 2015). "Similarly, of the myriad of known neutrophil specific immunodeficiencies caused by genetic abnormalities linked to Candida infection, including Dectin-1, CD18, CARD9, MPO, and enzymes of the NADPH oxidase pathway, to date chitotriosidase has not been linked in an increase in fungal susceptibility." (PMID 33796101, 2021). "Thus, the collective dependence on Card9 for neutrophil recruitment during pulmonary mold infections appears relatively mild compared to the universal reliance required for neutrophil accumulation and protection against Candida infection in the CNS." (PMID 27092298, 2016). "Strikingly, Candida infections involving the kidney, liver or spleen, the organs typically affected in patients with iatrogenic immunosuppression, have not been reported in CARD9-deficient patients." (PMID 27092298, 2016). "Thus, in this high-dose candidiasis model, Y91HKI phenocopy Card9–/– tissue susceptibility at 3 noncontiguous anatomical locations, suggesting that these mice have comparable defects in antifungal defenses." (PMID 40424070, 2025). "Additionally, CARD9 defects, while rare, lead to systemic candidiasis with potential central nervous system (CNS) involvement due to CARD9 expression on monocytes and macrophages, rather than mucosal forms of disease." (PMID 29371568, 2017).
immunodeficiencies (16 papers, 2015 to 2025). "In rare cases, deep dermatophytosis or disseminated fungal infection can occur, particularly in patients with primary immunodeficiencies, such as CARD9 (Caspase Recruitment Domain-containing protein 9) deficiency." (PMID 40278140, 2025). "Few cases of mucormycosis have also been reported among other primary immune deficiencies, including caspase recruitment domain-containing protein 9 (CARD9) deficiency and STAT1 gain-of-function." (PMID 36983475, 2023). "This group of patients usually were tricky to cure and had a long course of the disease, indicating that anti-fungal immunodeficiency caused by the CARD9 gene mutation was one of the pathogenic factors." (PMID 35770068, 2022). "For example, this system relies on immunocompetent larvae; however, patients with severe phaeohyphomycosis have underlying immune disorders such as CARD9 mutations." (PMID 37746169, 2022). "The discovery of rare inherited immune disorders, such as the one accompanying mutations in the caspase recruitment domain-containing protein 9 gene (CARD9), led to a paradigm change for the understanding of a number of severe fungal infections." (PMID 36003392, 2022). "Many genetic conditions are associated with congenital immune deficiencies, including CARD9 (caspase recruitment domain-containing protein 9) gene mutations." (PMID 34234782, 2021). "The diagnosis of severe either invasive or extensive dermatophytosis without clearly identifiable risk factors should lead to screening for inherited immunodeficiencies, such as CARD9 deficiency." (PMID 29376922, 2015). "PHM has been recently found related closely to some immune deficiencies which may be natural, especially the deficiency of the caspase recruitment domain-containing protein 9 (CARD9) gene or acquired." (PMID 35770068, 2022). "Given the severity of the case, the recurrence of the fungus over decades, and the occurrence of similar infections in family members, a rare inherited immune disorder such as homozygous mutations in the CARD9 gene involved in the C-type lectin pathway may be surmised." (PMID 28179902, 2017). "Inherited CARD9-related immune disorders and their clinical significance have first been reported somewhat over a decade ago." (PMID 36003392, 2022). "A large portion of PHM patients without known immunodeficiencies may have the potential mutations of the CARD9 gene if the gene test could be done in the past." (PMID 35770068, 2022).
Obesity (14 papers, 2017 to 2025). Accumulation of substantial excess body fat. "Lastly, CARD9 deletion restored the dysfunctional myocardial autophagy associated with HFD-induced obesity." (PMID 40710299, 2025). "CARD9, a scaffolding protein, has been implicated in the pathogenesis of metabolic diseases, including obesity and diabetes." (PMID 37958977, 2023). "Cao and coworkers demonstrated that CARD9 knockout ameliorates myocardial dysfunction associated with high-fat-diet-induced obesity via the suppression of p38 MAPK phosphorylation and preservation of autophagy in the heart." (PMID 37958977, 2023). "In the current study, we explored a positive feedback signalling cycle of dysregulated lipolysis, CARD9‐associated inflammation, impaired lipophagy and excessive LD accumulation in sustaining the chronic inflammation associated with obesity." (PMID 35962606, 2022). "Previously, the caspase recruitment domain‐containing protein 9 (CARD9) has been identified as a potential contributor to obesity‐associated abnormalities including cardiac dysfunction." (PMID 35962606, 2022). "As defects in macrophage autophagy were associated with chronic inflammation in obesity, next, we tested if CARD9‐dependent inflammation alters autophagy in PMs of HFD‐fed WT mice." (PMID 35962606, 2022). "It was concluded that the deletion of CARD9 might afford protection against metabolic dysfunction associated with diet-induced obesity, presumably mediated via the CARD9-MAPK signaling axis." (PMID 40710299, 2025). "Our findings suggest that CARD9 may server as a potential therapeutic target in suppressing chronic inflammation associated with obesity and related metabolic disorders characterized by defective lipid metabolism." (PMID 35962606, 2022). "MT-KO combined with HFD-induced obesity synergistically promotes cardiac remodeling, possibly via trace metal dyshomeostasis-induced oxidative stress to trigger CARD9/BCL10-mediated NF-κB activation." (PMID 39897024, 2025). "We observed that obesity induces cardiac hypertrophy by activating p38 MAPK through CARD9/BCL10 complex upregulation, which was assumed to be mediated by increased oxidative stress 10,19." (PMID 39897024, 2025). "Owing to the common link of MT and CARD9 signaling with inflammation, we preliminarily explored these interactions in obesity cardiomyopathy." (PMID 39897024, 2025). "The inflammatory changes observed herein suggest that obesity and MT-KO synergistically affected macrophage infiltration in the heart, proinflammatory cytokine production, CARD9 signaling pathway activation, and, by extension, cardiac hypertrophy and fibrosis." (PMID 39897024, 2025). "The deletion of CARD9 also afforded protection against obesity-induced myocardial dysregulation, interstitial fibrosis, and the infiltration of macrophages into the heart." (PMID 40710299, 2025). "For example, using a CARD9 knockout animal model, Zeng and coworkers investigated the roles of this scaffolding protein in high-fat diet (HFD)-induced obesity and associated metabolic complications." (PMID 40710299, 2025). "Along these lines, Cao and coworkers investigated the regulatory roles of CARD9 in HFD-induced and obesity-associated myocardial dysregulation in these animals." (PMID 40710299, 2025). "Previously, caspase recruitment domain-containing protein 9 (CARD9) has been identified as a potential contributor to obesity-related abnormalities." (PMID 38456906, 2024). "Recent evidence in animal models with CARD9 deletion demonstrated roles for CARD9 in diet-induced inflammation, obesity, and metabolic pathologies." (PMID 37958977, 2023). "In conclusion, our study demonstrated that HFD‐induced obesity is associated with dysregulated LD lipolysis in PMs, resulting in activation of DAG‐PKCδ signalling and CARD9‐dependent inflammation and impairment of lipophagy." (PMID 35962606, 2022).